INS (insulin)
Diseases named in the same sentence as INS in open-access papers (continued):
Sharing a sentence is not in itself a finding about the gene and the disease.
Insulin resistance (continued). "APP also potentiated glucose-stimulated insulin secretion and attenuated insulin resistance measured by HOMA-IR." (PMID 27216600, 2016). "When fed the normal chow diet, both male and female LPLΔhep mice did not display significant differences in blood glucose levels, fasting serum insulin levels, or homeostasis model assessment of insulin resistance compared with controls." (PMID 27234787, 2016). "Impaired postprandial insulin-mediated suppression of whole-body adipose tissue lipolysis has been reported in insulin resistance, although lipolysis per unit fat mass is reduced." (PMID 26985905, 2016). "Alternative and simpler methods of measuring insulin resistance include the fasting insulin level, the ‘homeostasis model assessment of insulin resistance’ (HOMA-IR), and the quantitative insulin sensitivity check index (QUICKI)." (PMID 27128847, 2016). "We focused particularly on single and double Akt phosphorylation and pointed out insulin signaling changes related to insulin resistance." (PMID 27149630, 2016). "Obesity was associated with increased serum levels of glucose, triglycerides, VLDL-cholesterol, and insulin, which are manifestations of insulin resistance." (PMID 26788524, 2016). "The effects of a high fat diet on body weight and insulin sensitivity have been reported previously, and it is generally known that anesthesia can induce insulin resistance." (PMID 27802272, 2016). "To further investigate the molecular basis of insulin resistance in Gnmt−/− mice, we analyzed insulin-stimulated signaling in the liver." (PMID 27716281, 2016). "Hepatic insulin resistance, hyperglycemia, and reduced glucose-induced insulin secretion were induced by the LPS infusion." (PMID 27617200, 2016). "Skeletal muscle is regarded as the main destination for insulin-stimulated glucose disposal and individuals with insulin resistance have increased intramuscular lipid content compared to insulin-sensitive control subjects." (PMID 27313625, 2016). "In this study, it was demonstrated that the lack of Insr expression and increased level of miR-135, contributed to the poor stimulation of glucose uptake by insulin in C2C12 cell line developing insulin resistance phenotype." (PMID 27602317, 2016). "With this value, we found that the prevalence of high salivary insulin concentration, indicating a state of insulin resistance and hyperinsulinemia, was increased in obese adolescents." (PMID 27069678, 2016). "Many studies have reported increasing insulin resistance and declining glucose tolerance concomitant with abnormal insulin secretion as characteristics of aging in both humans and experimental animals." (PMID 27441644, 2016). "Theoretically, a large influx of fructose into the liver causes accumulation of triglycerides and cholesterol because of its lipogenic (fat-producing) properties, subsequently leading to reduced insulin sensitivity, insulin resistance and glucose intolerance." (PMID 27708685, 2016). "Although we observed a strong upregulation of hepatic Vnn1 expression and plasma vanin activity in obese, insulin resistant mice and rats, our results suggest that vanin-1 only plays a minor role in the pathophysiology of insulin resistance." (PMID 26932716, 2016). "In the liver, insulin‐resistance increases hepatic production of glucose by gluconeogenesis and glycogen breakdown (which is normally suppressed by post‐prandial insulin action), contributing to hyperglycaemia." (PMID 26467985, 2016). "Elderly healthy men (67–80 years) also show deterioration in glucose homeostasis as evidenced by insulin resistance, defective insulin secretion, and insulin action." (PMID 27441644, 2016). "SOCS3 is a major negative regulator of insulin and leptin signaling and is thought to contribute to the pathogenesis of insulin resistance." (PMID 27337171, 2016).
Insulin resistance (continued). "We also examined the other possibility that inactivity‐induced rapid development of insulin resistance is associated with reduced phosphorylation of AS160, the most distal insulin‐signaling protein that have been linked to the regulation of glucose uptake." (PMID 27482072, 2016). "In Japanese subjects, decreased insulin secretion has a greater impact on the incidence of type 2 diabetes than increased insulin resistance." (PMID 27612202, 2016). "Chemerin induces insulin resistance in muscle cells and promotes insulin sensitivity in adipocytes in vitro." (PMID 26873079, 2016). "Excess ROS activate stress and mitogen activated protein kinase signaling pathways in insulin sensitive tissues contributing to the development of insulin resistance and type 2 diabetes." (PMID 28119617, 2016). "We have previously reported increased insulin and insulin resistance in obese women the morning following acute nighttime protein ingestion." (PMID 27472361, 2016). "Proinflammatory cytokines and other molecules that are produced by adipocytes, macrophages, and other infiltrating immune cells can disrupt normal insulin signaling and glucose transport inducing insulin resistance." (PMID 27006824, 2016). "Insulin resistance (IR), defined as decreased glucose uptake and disposal ability, along with defects in insulin secretion, are fundamental elements in the aetiology of T2D." (PMID 28443211, 2016). "One of the consequences of prolonged HFD feeding is the development of obesity-related insulin resistance which stems from a combination of altered function of insulin target cells and the accumulation of inflammatory macrophages in WAT (refs 3, 32)." (PMID 27464507, 2016). "A different group of studies have described BPA mechanisms of action on the insulin-sensitive peripheral tissues involved in the development of insulin resistance, including adipose tissue, skeletal muscle, and the liver." (PMID 27782064, 2016). "Hepatic insulin resistance leads to severely dysregulated glucose homeostasis, resulting in or contributing to hyperglycemia, which then further worsens hepatic insulin insensitivity." (PMID 26959059, 2016). "In future studies, an initial assessment of insulin resistance and glucose tolerance should precede the randomization process to fully elucidate the effect of exenatide on insulin secretion in obese cats." (PMID 27136422, 2016). "It is possible that rapa-treatment generally diminishes insulin resistance in diabetic mice, but that sustained, excessive circulating insulin, characteristic of the two KK models, over-whelms this effect." (PMID 27922820, 2016). "The failure of target organs to respond to the normal action of insulin is termed insulin resistance, which in turn often results in compensatory hyperinsulinemia." (PMID 26999199, 2016). "One study indicated that the activation of p42/p44 and p38 MAPK by TNFα impaired insulin stimulation of IRS-2 associated PI3K, leading to insulin resistance in brown adipocytes." (PMID 26903879, 2016). "Whole-body insulin resistance and its improvement are the result of the combined actions of each insulin-sensitive organ." (PMID 28025491, 2016). "Patients with a HOMA-IR of 2.5 or higher are regarded as being resistant to insulin, and 25 % of patients in this study (low dose group: 5 out of 20 patients, high dose group: 4 out of 16 patients) exhibited insulin resistance after 260 weeks of GH therapy." (PMID 27799945, 2016). "Under conditions of insulin resistance, peripheral tissues fail to respond to insulin, resulting in hyperglycemia, dysregulated glycogen synthesis and elevation of circulating free fatty acids from inappropriate lipolysis." (PMID 27053133, 2016). "Using C2C12 myoblasts, we showed that celecoxib was able to reverse PA-induced insulin desensitization, restoring Akt phosphorylation, and thus demonstrating a mechanism by which celecoxib protects muscle from insulin resistance." (PMID 26899878, 2016).
Insulin resistance (continued). "In the presence of normal pancreatic cell function, puberty‐related insulin resistance is compensated by increased insulin secretion." (PMID 26887327, 2016). "Insulin resistance in the context of preserved target-cell signaling and intracellular pathways can also be induced by interference with the binding of insulin to InR." (PMID 27053133, 2016). "The pathogenesis of type 2 DM includes insulin resistance and an insulin secretory response that is inadequate in fulfilling biological requirements." (PMID 27893867, 2016). "Adipose tissue de novo lipogenesis (DNL) positively influences insulin sensitivity, is reduced in obesity, and predicts insulin resistance." (PMID 27098609, 2016). "We chose the HOMA-IR estimate of insulin resistance during the meal tolerance tests in part because it allows assessment of the physiological contribution of intestinal incretins to insulin secretion." (PMID 27798656, 2016). "We also aimed to explore possible pathways among circulating irisin, adiposity, glucose and insulin levels and insulin resistance." (PMID 27473122, 2016). "The M1 phenotype of macrophages can alter insulin signaling pathways and adipogenesis in adipocytes while M2 macrophages appear to safeguard against obesity-induced insulin resistance." (PMID 27527213, 2016). "In a recent study, an intraduodenal infusion of RSV improved insulin sensitivity and lowered hepatic glucose production in three rat models of insulin resistance." (PMID 28050570, 2016). "Insulin sensitivity and inflammation have been shown to influence both growth and ovarian function; in particular there is wide evidence that polycystic ovarian syndrome (PCOS) originates from insulin resistance and from excessive exposure to insulin." (PMID 27746590, 2016). "Fasting blood glucose and insulin, and homeostasis model assessment of insulin resistance (HOMA-IR) served as surrogate markers of insulin resistance." (PMID 27829488, 2016). "Eight of these substances were further tested on glucocorticoid-induced insulin resistance models, namely glucose tolerance, oral rapid insulin, and adrenalin tests." (PMID 27222601, 2016). "For this purpose we generated a GFP-labelled biosensor based on FoxO1, a transcription factor that resides in the cytoplasm in insulin-sensitive cells and translocates into the nucleus under conditions of insulin resistance." (PMID 26899548, 2016). "Insulin resistance (IR) is a disorder characterized by an impaired metabolic response to either exogenous or endogenous insulin, with consequences on carbohydrate, lipid and protein metabolism." (PMID 26875986, 2016). "Nevertheless, in ages up to 20 months, the increase in insulin secretion is able to compensate for the insulin resistance, and these results in the increase in glucose tolerance seen in C57BL/6J mice." (PMID 27441644, 2016). "Taken together, these reports from Korea perhaps suggest that the insulin secretory capacity of Korean people, who are smaller than Western people, cannot compensate for the insulin resistance resulting from recent changes in their life style." (PMID 27275953, 2016). "We also confirmed that this stimulatory effect of insulin on NBCe1 in the PT is preserved in humans with insulin resistance as well." (PMID 27247938, 2016). "In these models, an early decrease in insulin sensitivity in the aorta (after 1–2 weeks feeding an HFD) is followed by the development of insulin resistance in the skeletal muscle and liver (8 weeks) and then in the adipose tissue (14 weeks)." (PMID 27128347, 2016). "At present, it is known that impaired insulin sensitivity and increased insulin resistance are profoundly involved in the progression of type 2 diabetes; and therapies improving or enhancing insulin sensitivity are being sought." (PMID 27141227, 2016). "TNFα induces insulin resistance by direct down-regulation of the insulin-regulatable glucose transporter type 4 (GLUT-4)." (PMID 27877101, 2016).
Insulin resistance (continued). "These examples of type 1 DM also showed the restricted role of MetS on DR in DM patient groups that showed a relative dominance of an insulin secretory defect over insulin resistance." (PMID 27275953, 2016). "Maternal insulin sensitivity will be derived from the homeostatic model assessment for insulin resistance (HOMA-IR), which will be calculated using the formula [fasting insulin (μIU/mL) × fasting glucose (mg/dL)]/405 in the 34th week of gestation." (PMID 27680325, 2016). "In this study, we tested the nutrient-induced insulin output ratio (NIOR), which is used to identify the correlation between the variants of genes and insulin resistance." (PMID 27455252, 2016). "Insulin resistance has been characterized as attenuation of insulin sensitivity at target organs and tissues, such as muscle and fat tissues and the liver." (PMID 27247938, 2016). "Here it was observed that hepatic diacylglycerol content from liver biopsy specimens was the strongest predictor of insulin resistance and accounted for 64% of the variability in insulin sensitivity." (PMID 26978356, 2016). "Mice became profoundly hyperinsulinemic and insulin intolerant, suggesting the acquisition of insulin resistance, and were clearly glucose intolerant." (PMID 26770990, 2016). "We found higher levels of triglycerides, insulin, homeostasis model assessment of insulin resistance (HOMA2-IR), and liver fat percentage in RYGB at baseline, despite matching the groups for age, sex, and BMI." (PMID 27003699, 2016). "Insulin-stimulated pAKTT308 and pAKTS473 are both attenuated in RictorAdipoq-cre livers consistent with hepatic insulin-resistance." (PMID 27098609, 2016). "An improved understanding of both normal insulin signalling and cellular insulin resistance will guide the development of new therapies targeting this axis." (PMID 27577745, 2016). "Since systemic insulin resistance is a common comorbidity in obese individuals, we performed insulin tolerance tests (ITTs) on animals of each genotype." (PMID 27832814, 2016). "Plasma insulin responses were improved (p < 0.01) and insulin resistance was decreased (p < 0.05 or p < 0.01) in both Abn-CBD- and AS-1269574-treated groups." (PMID 27677765, 2016). "Participant characteristics (i.e., low BMI, low insulin secretion, and low insulin resistance) are comparable to those of Asian T2DM patients previously reported." (PMID 26925169, 2016). "With the relationship between complications and insulin resistance established, potential adjuvant strategies which would improve the insulin sensitivity of those with T1DM would be considered of paramount importance." (PMID 27581061, 2016). "Markers of insulin signaling indicate an activation of intrinsic pulmonary insulin signaling at an early phase (P21) and features of insulin resistance at a late phase (P70)." (PMID 27087690, 2016). "We aimed to examine the effect of HUA on insulin sensitivity in cardiomyocytes and on insulin resistance in hyperuricemic mouse model." (PMID 26836389, 2016). "TSH showed positivecorrelations with BMI, hsCRP, fasting glucose,fasting insulin, insulin resistance, LH/FSH ratioand prolactin (r=0.173, P<0.05, r=0.757,r=0.772, r=0.499, r=0.583, r=0.492, r=0.693, respectively and P<0.01)." (PMID 27123196, 2016). "Low insulin sensitivity is known as insulin resistance and is affected by obesity, inflammation, exercise, pregnancy, and genetics." (PMID 27875241, 2016). "As expected, HFD increased most metabolic parameters in both WT and CKO mice, including body weight, epididymal fat mass, plasma triglycerides, LDL/VLDL, fed and fasting insulin, and homeostatic model assessment-insulin resistance (HOMA-IR)." (PMID 27597806, 2016). "Second, intra-abdominal obesity promotes insulin resistance, a state of reduced responsiveness of tissues to the physiologic actions of insulin." (PMID 27294726, 2016).
Insulin resistance (continued). "In obesity, excess triglycerides promote the lipolysis and release of free fatty acids (FFA), which results in the dysfunction of insulin action and in insulin resistance." (PMID 27869712, 2016). "High insulin resistance interferes with the stimulatory effects of insulin on peripheral glucose uptake." (PMID 27483133, 2016). "During the development of T2D, peripheral insulin resistance leads to hyperglycemia and initially triggers a compensatory response from the β-cells to release more insulin." (PMID 28123396, 2016). "Fenofibrate therapy significantly reduced insulin concentration in MetS rats and restored insulin resistance index (HOMA-IR)." (PMID 28036029, 2016). "Increasing evidences support that the presence of insulin resistance, characterized as impaired insulin-stimulated glucose and/or lipid metabolism, represents early events in individuals at high risk for developing CVD." (PMID 27616738, 2016). "Since there is a compensatory increase in insulin secretion under conditions of insulin resistance, we further examined the correlation with adjustment for HOMA-R, which did not change its significance (ß = -0.057, p = 0.034)." (PMID 27861636, 2016). "In the present study, we evaluated the correlation between average GCIPL thickness and the parameters of insulin resistance such as plasma insulin level, BMI value, and HOMA-IR value." (PMID 28050322, 2016). "These defects lead to an impaired capacity of insulin to regulate whole body glucose homeostasis, a condition commonly known as “insulin resistance”." (PMID 28248217, 2016). "Many studies suggested that insulin resistance is also a process of chronic inflammation and that interactions exist between the inflammation and insulin signaling pathways." (PMID 27187341, 2016). "It is also known that systemic inflammation blocks insulin signaling pathways, leading to insulin resistance and glucose intolerance, which are the driving force for hepatic steatosis." (PMID 27895587, 2016). "Hepatic insulin resistance refers to the impaired ability of insulin to suppress hepatic glucose production, despite rather elevated circulating insulin levels." (PMID 27708333, 2016). "Because of the challenges in determining insulin resistance in dolphins, we decided to investigate hormonal changes in the insulin sensitizing FGF21/adiponectin/ceramide axis that would be consistent with improving insulin sensitivity." (PMID 27148164, 2016). "P. trifoliata extracts reduced insulin resistance as indicated by reduced insulin and HOMA-IR levels, and the fruit-extract-treated HFD mice showed lower blood glucose levels than those of water-treated HFD mice at 60, 90 and 120 min during the OGTT." (PMID 27058520, 2016). "Fasting insulin and Homeostatis Model Assessment of Insulin Resistance (HOMA-IR) were increased after 12 weeks of fructose-feeding." (PMID 27818793, 2016). "Insuline resistance should be evaluated by HOMA INDEX (product of fasting plasma insulin [mU/L] and glucose [mmol/L] concentrations divided by 22.5)." (PMID 27423183, 2016). "It is plausible that intranasal insulin treatment can ameliorate insulin resistance due to increased IRS1pSer, leading to a reduction in Aβ production and amyloid plaque burden, and improvement of cognition." (PMID 27457264, 2016). "It seems that, rather than changes in GI peptide secretion, fasting hyperglucagonemia and consequent hyperglycemia play a role in reduced disposal of insulin, contributing to hyperinsulinemia and insulin resistance." (PMID 26942445, 2016). "Insulin resistance is characterized by inability of insulin to exert its signaling effects, mainly due to dysfunction at the level of IRS1 and IRS2 activation and PI3K recruitment to the plasma membrane." (PMID 27434075, 2016). "Insulin function was represented with two indexes: insulin resistance index (HOMA-IR) and insulin secretion index (HOMA-B) estimated by homeostasis model assessment." (PMID 27992538, 2016).